GDF15 (growth differentiation factor 15)
Diseases named in the same sentence as GDF15 in open-access papers (continued):
Sharing a sentence is not in itself a finding about the gene and the disease.
myocardial infarction (continued). "Our results provide novel insights into the molecular mechanisms of GDF-15-mediated cardioprotection and suggest its potential as a therapeutic intervention for myocardial infarction." (PMID 41023695, 2025). "Experimental models in mice demonstrate a nearly 20-fold increase in myocardial GDF15 mRNA following myocardial infarction relative to uninjured hearts." (PMID 40806859, 2025). "Studies have shown that GDF15 is a highly predictive biomarker of cardiovascular events and mortality in patients with heart disease and myocardial infarction [1260, 1261]." (PMID 40407975, 2025). "In the context of cardiac injury, GDF15 levels rise sharply in infarcted myocardium compared to the levels in healthy tissue, and plasma concentrations increase following acute myocardial infarction." (PMID 40723863, 2025). "Some preclinical animal studies have shown that GDF-15 can protect mice from CR after myocardial infarction by inhibiting the activation of chemokine-triggered leukocyte integrin." (PMID 38429673, 2024). "Indeed, several studies demonstrated that increased GDF-15 production is significantly associated with some metabolic (including obesity and diabetes mellitus) and cardiovascular diseases (including coronary artery disease and myocardial infarction), as recently reviewed in detail." (PMID 36614282, 2023). "The plasma concentration of GDF-15 increases within a few hours of the onset of a myocardial infarction and remains elevated for several days." (PMID 38255650, 2023). "In recent years, there has been increasing literature on the role of GDF-15 as a prognostic biomarker in the acute care setting, including sepsis, renal disease, chronic obstructive airway disease, COVID-19, and myocardial infarction." (PMID 37152099, 2023). "Despite the incomplete understanding of GDF-15s role, we are already aware of its high predictive value for worse prognosis in patients presenting higher concentrations of GDF-15 during myocardial infarction." (PMID 36615045, 2022). "GDF-15 is expressed in cardiac tissue in patients with myocardial infarction and in experimental models of pressure overload and cardiac hypertrophy, potentially contributing to myocardial remodeling." (PMID 34611778, 2022). "On the contrary, it has also been shown that GDF15 inhibited inflammatory cell recruitment in myocardial infarction, thus directly counteracting chemokine signaling and integrin activation." (PMID 35993367, 2022). "The combination of GDF-15 and TRAIL-R2 was a better predictor of long-term all-cause mortality in patients with acute myocardial infarction in a study from 2017." (PMID 35204357, 2022). "The concentration of GDF15 was shown to correlate with the severity of coronary artery disease in patients with a suspected myocardial infarction and was an independent predictor of future cardiovascular events in those patients." (PMID 34830700, 2021). "GDF15 expression is highly induced in cardiomyocytes after ischemia/reperfusion and in the heart within hours after myocardial infarction (MI)." (PMID 34445593, 2021). "GDF-15 levels increase in just a few hours after a myocardial infarction and remain elevated for a few days." (PMID 34821692, 2021). "In skeletal muscle and the heart, the basal expression of GDF15 is very low compared to other organs, but GDF15 expression and secretion can be induced in various stress conditions, such as intense exercise and acute myocardial infarction, respectively." (PMID 34831213, 2021). "Induction of GDF-15 after myocardial infarction was shown to be essential for limiting the recruitment of polymorphonuclear leukocytes (PMNs), thereby permitting infarct healing without causing cardiac rupture." (PMID 32508832, 2020). "With particular emphasis on its immunomodulatory potential this review discusses the roles of GDF-15 in pregnancy and in pathological conditions including myocardial infarction, autoimmune disease, and specifically cancer." (PMID 32508832, 2020).
myocardial infarction (continued). "A small study using high-frequency sampling of blood from patients after acute coronary syndrome has illustrated the temporal trend in GDF15 following myocardial infarction." (PMID 32310257, 2020). "Knockout of GDF-15 in mice augments inflammation and increases cardiac rupture following myocardial infarction." (PMID 33041853, 2020). "Our findings and conclusions are consistent with previous observations in a mouse model of myocardial infarction where Gdf15−/− mice recruited more neutrophils to the injury site." (PMID 32424099, 2020). "GDF15 is upregulated in infarcted human myocardium relative to remote, noninjured myocardium and is elevated in the blood of individuals after myocardial infarction." (PMID 32310257, 2020). "Briefly, an examination of the role of GDF15 in myocardial infarction has suggested an anti-inflammatory action of GDF15." (PMID 32310257, 2020). "In this retrospectively observational study, we aimed to determine the role of GDF-15 and the risk of AKI in acute myocardial infarction (AMI) patients." (PMID 29529072, 2018). "Increased expression of GDF-15 was observed in the human heart within hours after myocardial infarction and remains elevated in the infarcted myocardium for several days." (PMID 27311391, 2016). "Recent study demonstrated that GDF-15 protects against fatal cardiac rupture in a mouse model of myocardial infarction." (PMID 26273671, 2015). "Increased expression of GDF-15 was observed in the mouse and human heart within hours after myocardial infarction and remains elevated in the infarcted myocardium for several days." (PMID 26273671, 2015). "GDF15 is weakly expressed in most tissues, but its expression is induced in response to tissue injury, notably in the heart following myocardial infarction." (PMID 26352141, 2015). "Patients with GDF-15 levels >1200 ng/L, especially those with 1800 ng/L experienced significant reduction in the combined end point of death or myocardial infarction by the routine invasive strategy." (PMID 26273671, 2015). "GDF-15 showed antiapoptotic effect against ischemia reperfusion (I/R) and reduced the size of myocardial infarction (MI)." (PMID 26273671, 2015). "Recently, elevated circulating GDF-15 levels that measured in individuals with acute myocardial infarction have been correlated with inflammatory biomarkers, suggesting a link between GDF-15 and inflammation." (PMID 26273671, 2015). "Several clinical studies have clearly demonstrated that GDF-15 was a strong biomarker of cardiovascular disease, and a prognosis marker of fatal events in patients with myocardial infarction and chronic HF." (PMID 25171167, 2014). "Gdf15 inhibits leukocyte integrin activation thus reducing inflammatory cell recruitment after myocardial infarction, a finding in agreement with the reduced leukocytes recruitment observed in LPS-treated Tmprss6 KO mice." (PMID 23922777, 2013). "The meta-analysis used hazard ratios (HR) and odds ratios (OR) to compare outcomes such as all-cause mortality, cardiovascular death, postoperative atrial fibrillation (AF), acute kidney injury (AKI), and spontaneous myocardial infarction (MI) between high GDF-15 levels and control groups." (PMID 40351689, 2025). "Furthermore, the observed reduction in HIF-1α expression following GDF15 administration underscores its role in mitigating the hypoxic stress integral to myocardial infarction." (PMID 41023695, 2025). "Intracranial GDF15 may also protect against organ damage by modulating inflammatory cell recruitment, as observed in myocardial infarction and early diabetic kidney disease models." (PMID 40854626, 2025). "For example, GDF-15 knockout mice demonstrated cardiac rupture after myocardial infarction." (PMID 38672115, 2024).
myocardial infarction (continued). "For example, in sepsis, GDF15 improves survival by promoting tissue tolerance against inflammatory damage; in heart ischemia and myocardial infarction, GDF15 exhibits anti-apoptotic and inflammatory effects by interfering with chemokine signaling and integrin activation in neutrophils." (PMID 38607075, 2024). "This study highlights that a single measurement of GDF15 upon admission offers independent prognostic information on the risks of death and recurrent myocardial infarction, thereby improving the identification of patients who will benefit from an invasive strategy." (PMID 39766300, 2024). "In the context of allogeneic transplantation of cardiac progenitor cells (CPCs) as a therapy for myocardial infarction, downregulation of GDF-15 in CPCs resulted in decreased activation of Tregs and M2 macrophages, preventing an adequate engraftment into the injured myocardium." (PMID 39000420, 2024). "For example, GDF15 hinders recruitment of polymorphonuclear leukocytes into myocardial infarcts and may limit occurrence of cardiac rupture." (PMID 39737171, 2024). "In addition toindependent risk indicators such as, age, N-terminal pro-brain natriureticpeptide (NT-proBNP), and myocardial infarction, GDF-15 was the most importantpredictor of death in this study." (PMID 39077481, 2023). "Thus, we decided to establish if there is any correlation between GDF-15 concentration and disturbances affecting microcirculatory reflow in patients with myocardial infarction after primary percutaneous coronary intervention (PCI)." (PMID 36615045, 2022). "Furthermore, after myocardial infarction, GDF-15 induction permitted infarct healing by limiting polymorphonuclear leucocyte (PMN) recruitment." (PMID 34221186, 2021). "GDF15 could ameliorate myocardial infarction by inhibiting polymorphonuclear leukocyte infiltration." (PMID 33567936, 2021). "Recent results obtained in our laboratory suggest that GDF15 could be an integrative biomarker for severe in-hospital HF (defined as Killip class > 2) in patients with acute myocardial infarction (AMI)." (PMID 34445593, 2021). "In addition, GDF15 predicts the development of acute kidney injury post cardiac surgery and after treatment of acute myocardial infarction with percutaneous coronary intervention or coronary artery bypass grafting." (PMID 32310257, 2020). "In addition, GDF15 is upregulated in experimental models of myocardial infarction in mice and in response to oxidative stress in cultured cardiomyocytes." (PMID 32310257, 2020). "Also, the serum level of TNC and GDF-15 was correlated with serum CK-MB which is considered an important marker for the myocardial infarction." (PMID 33312062, 2020). "Also, GDF-15 had an antiapoptotic effect against ischemia-reperfusion and reduced the size of myocardial infarction." (PMID 33312062, 2020). "High levels of GDF-15 are associated with increased risks of outcomes in patients with coronary no-reflow, acute myocardial infarction and renal dysfunction." (PMID 29791474, 2018). "For example, GDF15 may act anti-inflammatory by limiting neutrophilic inflammation as seen in myocardial infarction." (PMID 30533221, 2018). "GDF15 had a higher baseline level among women who were participants in the Women's Health Study who eventually developed cardiovascular-related disease states including thrombosis, stroke, and myocardial infarction." (PMID 29967567, 2018). "In a murine warm I/R injury model induced by coronary artery ligation, GDF15 has been demonstrated to protect the heart from I/R injury through inhibition of leukocyte integrin activation in response to permanent and transient myocardial infarction." (PMID 28388574, 2017). "In patients with GDF-15 levels exceeding 4638 ng/l, further cardiac diagnosis and medical intervention should be considered because myocardial infarction or myocardial necrosis may be indicated." (PMID 27311391, 2016).
myocardial infarction (continued). "GDF-15 was a reliable biomarker of fatal events in patients with acute myocardial infarction." (PMID 27311391, 2016). "Thus, GDF-15 is an inhibitor of leukocyte integrin that is one of the essential components to induce cellular injury after myocardial infarction." (PMID 26273671, 2015). "It is pointed that GDF-15 level is associated with the risk of death and myocardial infarction independent of clinical variables and other biomarkers." (PMID 26075263, 2015). "Accumulating evidence indicates that circulating levels of GDF-15 are associated with the risk of death and myocardial infarction, independent of clinical variables and other biomarkers, including hsCRP and cardiac troponins." (PMID 24839357, 2014). "In Myocardial Infarction (MI), GDF-15 pro-peptide levels increased, reached maximum levels after 6 hours, and returned toward baseline after 12 hours." (PMID 39781722, 2025). "To investigate the role of GDF15 in myocardial infarction (MI), we initially examined its expression pattern in heart tissues from MI mice." (PMID 41023695, 2025). "However, GDF-15 mediates anti-inflammatory effects in mice with acute myocardial infarction." (PMID 37371667, 2023). "Additionally, multiple studies have demonstrated that increased levels of GDF-15 are associated with the presence of stable CAD, with higher concentrations found in patients with multivessel coronary disease and those with a history of myocardial infarction." (PMID 38255650, 2023). "GDF15 concentrations have been associated with total and cardiovascular mortality and inconsistently with nonfatal myocardial infarction, and GDF15 has been proposed as a biomarker for cardiovascular events and all-cause mortality in the general population and PLWH." (PMID 35160008, 2022). "For instance, GDF-15 expression increases in macrophages and may have proinflammatory effects in atherosclerosis, whereas anti-inflammatory effects have been observed in acute diseases such as myocardial infarction." (PMID 31258506, 2019). "As a biomarker, GDF-15 has widely been studied in cardiovascular diseases where it is considered as an independent marker of poor prognosis in patients with coronary artery disease, acute myocardial infarction, atrial fibrillation, and heart failure with preserved or reduced ejection fraction." (PMID 31258506, 2019). "Interestingly, in mouse models of cardiac hypertrophy and myocardial infarction, GDF15 acts as a novel autocrine/endocrine factor that antagonizes the hypertrophic response and loss of ventricular performance, thereby preventing myocardial apoptosis and limiting infarct size." (PMID 24069374, 2013). "However, high GDF-15 concentrations showed limited predictive value for myocardial infarction (MI) in patients with CAD, particularly in those with acute coronary syndrome (ACS)." (PMID 41590509, 2026). "Despite all the protective effects of GDF-15, clinical studies in patients with DCM have shown that elevated GDF-15 levels correlate with adverse cardiovascular outcomes, including HF, myocardial infarction, and mortality." (PMID 38672115, 2024). "Skau E, Henriksen E, Wagner P, Hedberg P, Siegbahn A, Leppert J. GDF-15 and TRAIL-R2 are powerful predictors of long-term mortality in patients with acute myocardial infarction." (PMID 33566936, 2021). "Also, GDF-15 increases the predictive value of the GRACE (Global Registry of Acute Coronary Events) score in patients with NSTEMI myocardial infarction, even more than NT-proBNP and may thus be useful in the risk stratification for choosing an invasive treatment." (PMID 34821692, 2021). "Multivariate analysis showed that delta GDF-15 (OR = 52.3, CI 95% 7-388.5, P < 0.001) was the unique independent predictor of the combined endpoint (class IIIB unstable angina and myocardial infarction) at 36-month followup." (PMID 24839357, 2014).
myocardial infarction (continued). "For the composite outcome of cardiovascular death, nonfatal ischemic stroke, nonfatal systemic embolism, or nonfatal myocardial infarction, 5 biomarkers including d-dimer, GDF-15, IL-6, NT-proBNP and hsTropT independently contributed to the model fit." (PMID 40744929, 2025). "The relationship between higher GDF-15 concentration and poor outcomes in this group of patients is unclear, especially taking into consideration the potentially protective functions of GDF-15 described in experimental models of myocardial infarction." (PMID 36615045, 2022). "Similarly, in a study on 847 patients with myocardial infarction (MI), using The Proximity Extension Assay proteomics chip (capable to analyze 92 different cardiovascular biomarkers), GDF-15 and TRAIL receptor 2 were identified as the best biomarkers in predicting long-term all-cause mortality." (PMID 35872912, 2022). "The MERLIN-TIMI study focused on the prognostic value of GDF15 in a population of 4330 non-ST-segment elevation (NSTE) myocardial infarction (NSTEMI) patients." (PMID 34445593, 2021). "However, there is no MR study to explore the causal relationship of GDF-15 level with major CVDs, such as stroke, AF, HF and myocardial infarction (MI)." (PMID 33115406, 2020). "Although ICG-001 treatment consistently increased the expression of Gdf15, Kit and Sdf1 at both day7 and day10 in rat hearts after myocardial infarction, we did not observe statistically significant changes." (PMID 24069374, 2013). "Likewise, serum GDF15 levels were found to be increased in patients with peripheral artery disease, but not in patients with stroke or previous myocardial infarction." (PMID 41008541, 2025). "Although GDF-15 has been noted for its anti-apoptotic, anti-inflammatory, and antihypertrophic actions, it also noted that elevated values of GDF-15 were found to correlate with a number of cardiac diseases, including LV hypertrophy, stable coronary artery disease, myocardial infarction, and HF." (PMID 35741176, 2022). "In addition, BMI, frequency of previous myocardial infarction, and percentage of never smokers tended to be higher in higher GDF-15 quartiles." (PMID 32993054, 2020). "In univariate analysis advanced age (age >75 years), ACS on presentation, history of myocardial infarction (MI), current smoking status, elevated BMI (>25 kg/m2), AHG in those patients with ACS, DM, CKD, CRP and NYHA ≥2 were significant determinants of elevated GDF-15 plasma levels." (PMID 27056183, 2016). "The FRISC II study showed that GDF15 may improve risk stratification in NSTE-ACS patients and demonstrated that elevated levels of GDF15 independently predicted risk of death or recurrent myocardial infarction in patients not treated with revascularization." (PMID 41303556, 2025). "Additionally, blood samples were obtained from patientswith stable CAD, demonstrating that higher GDF-15 plasma concentrations atbaseline were associated with an increased event rate of the primary compositeend point (death from CVD, nonfatal myocardial infarction, or nonfatal stroke)." (PMID 39077481, 2023). "GDF-15 is considered to be an important biomarker for cardiovascular events, but the differences in serum GDF-15 levels between acute myocardial infarction (AMI) patients and non-AMI patients warrant further investigation." (PMID 31772623, 2019). "The majority of these patients (71%) were initially diagnosed with an acute myocardial infarction and had a poorer outcome compared to patients not in need for a PCI, likewise to patients with increased GDF-15 levels." (PMID 28771550, 2017).